TM6SF2 (transmembrane 6 superfamily member 2)
Diseases named in the same sentence as TM6SF2 in open-access papers (continued):
Sharing a sentence is not in itself a finding about the gene and the disease.
liver fibrosis (34 papers, 2014 to 2026). "Upon univariable analyses, risk variants in PNPLA3 and TM6SF2 were associated with liver fibrosis as assessed by LSM (log-transformed), with a stronger association in the Tertiary-care cohort than the At-risk cohort." (PMID 41492318, 2026). "A common non-synonymous polymorphism in TM6SF2 rs58542926 was recently associated with increased hepatic triglyceride content, but also promotes clinically relevant hepatic fibrosis." (PMID 40640848, 2025). "Subsequently, we examined any potential role of PNPLA3 rs738409 and TM6SF2 rs58542926 variants in moderating predisposition to significant and advanced hepatic fibrosis, and liver cirrhosis in separate analyses." (PMID 36028802, 2022). "In summary, we found that the presence of T2D or significant IR, defined by a new proposed cut-off of HOMA-IR > 5.20, on top of PNPLA3 rs738409 and TM6SF2 rs58542926 polymorphisms were associated to advanced liver fibrosis." (PMID 35625751, 2022). "T2D (OR = 4.67; 95%CI 2.13–10.20; p < 0.001), PNPLA3 rs738409 and TM6SF2 rs58542926 polymorphisms (OR = 3.94; 95%CI 1.63–9.54; p = 0.002) were independently related with advanced liver fibrosis." (PMID 35625751, 2022). "The Glu167Lys (E167K) transmembrane 6 superfamily member 2 (TM6SF2) variant is a further genetic polymorphism associated with liver fibrosis, ALT levels and reduced liver-derived TG rich lipoproteins plasma levels." (PMID 31428049, 2019). "The key finding of the current study is that carriage of the TM6SF2 rs58542926 C>T minor allele is unequivocally associated with an increased risk of advanced NAFLD-associated hepatic fibrosis." (PMID 24978903, 2014). "Finally, the association between specific pattern of liver fibrosis and other genetic variants should be further tested, as recent evidence suggested that, TM6SF2 p.E167K, and MBOAT7 rs641738 variants are associated with increased liver steatosis and fibrosis." (PMID 29150621, 2017). "Consecutively, we studied prespecified factors known to be associated with liver fibrosis next to PNPLA3 and TM6SF2 risk alleles." (PMID 41492318, 2026). "This study investigated the role of the stress-response co-chaperone BAG3 as a circulating biomarker of hepatic fibrosis and its association with PNPLA3 and TM6SF2 genotypes." (PMID 41373448, 2025). "In a well-characterized Southern European cohort of 146 MASLD patients, liver fibrosis was assessed using the FIB-4 index, serum BAG3 levels were quantified by ELISA, and genotyping for PNPLA3 and TM6SF2 variants was performed." (PMID 41373448, 2025). "Exome‐wide association studies in SLD showed that the transmembrane 6 superfamily member 2 (TM6SF2) gene polymorphism (rs58542926) is involved in the development of SLD, steatohepatitis, and liver fibrosis." (PMID 38919271, 2024). "Clinical and epidemiological studies have confirmed the role of the TM6SF2 variant in the development of MAFLD, and TM6SF2 has also been shown to play an important role in promoting liver fibrosis and hepatocellular carcinoma in mouse models." (PMID 37753315, 2023). "In previous studies, the relationship of TM6SF2 rs58542926 with liver fibrosis has been controversial." (PMID 36353245, 2022). "Meta-analysis studies have also shown the E167K (rs58542926) polymorphism in TM6SF2 in NAFLD and other human diseases, such as carcinoma and liver fibrosis." (PMID 36557278, 2022). "Further studies are needed in order to validate and confirm our results, but it seems that IR mediates the risk of progression towards advanced liver fibrosis induced by PNPLA3 rs738409 and TM6SF2 rs58542926 polymorphisms." (PMID 35625751, 2022). "In the current study, we aimed to evaluate the associations between TM6SF2 rs58542926 and MBOAT7 rs641738 genes polymorphisms and the risk of hepatic fibrosis and liver cirrhosis." (PMID 30875804, 2019).
liver fibrosis (continued). "In this study we analyzed the association between TM6SF2 variant rs58542926 and MBOAT7 variant rs641738 and the risk of hepatic fibrosis or liver cirrhosis of different etiology in an Eastern European patient cohort." (PMID 30875804, 2019). "In this study, we tried to evaluate the association between TM6SF2 variant rs58542926 and MBOAT7 variant rs641738 and the risk of hepatic fibrosis or liver cirrhosis of different etiology." (PMID 30875804, 2019). "The effects of PNPLA3 have been well established in previous research, but we wanted to see if the risk of liver fibrosis is changed by a certain combination of PNPLA3 and TM6SF2 or MBOAT7 genotypes." (PMID 30875804, 2019). "Our findings indicate that PNPLA3 and TM6SF2 variants do not act as independent determinants of liver fibrosis once gene–environment interactions are considered." (PMID 41492318, 2026). "TM6SF2 (Transmembrane 6 Superfamily Member 2) is another key gene, with the rs58542926 C>T variant linked to higher liver fat accumulation by influencing the secretion of very low-density lipoprotein (VLDL) from hepatocytes as well as liver fibrosis." (PMID 41303369, 2025). "In this study, we explore the significance of BAG3 detection in patients’ sera in hepatic fibrosis within the context of MASLD and its interaction with key genetic variants PNPLA3 and TM6SF2, aiming to unravel potential new insights into the molecular mechanisms driving disease progression." (PMID 41373448, 2025). "However, the overactivation of these healing processes leads to the onset of progressive liver fibrosis, especially in individuals with increased susceptibility to liver fibrosis due to gene polymorphisms, such as PNPLA3, TM6SF2, and HSD17B13." (PMID 35563210, 2022). "Overall, TM6SF2 rs58542926 as well as MBOAT7rs641738 were not linked to hepatic fibrosis, alcohol or hepatitis C virus induced liver cirrhosis in an Eastern European population." (PMID 30875804, 2019). "In conclusion, TM6SF2 rs58542926 as well as MBOAT7 rs641738 were not linked to hepatic fibrosis, alcohol or hepatitis C virus induced liver cirrhosis in an Eastern European population." (PMID 30875804, 2019). "It is therefore tempting to speculate that the function of TM6SF2 and the mechanism through which TM6SF2 drives NAFLD-associated hepatic fibrosis may be other than through increased triglyceride accumulation." (PMID 24978903, 2014). "This is the first study to investigate the relationship between the PNPLA3 rs738409, TM6SF2 rs58542926, GCKR rs1260326 and rs780094, MBOAT7 rs641738, HSD17B13 rs72613567, and MTARC1 rs2642438 polymorphisms in the Brazilian population with MASLD and liver fibrosis." (PMID 40650184, 2025). "Thus, one study speculated that the function of TM6SF2 and the mechanism through which TM6SF2 drives MASLD‐associated hepatic fibrosis may be something other than increased TG accumulation." (PMID 38919271, 2024). "Notably, genetic polymorphism of TM6SF2 in the dominant model was independently linked to the risk of developing NAFLD, and PNPLA3 genetic variants additively increased vulnerability to NAFLD‐related hepatic fibrosis." (PMID 36403577, 2023). "In addition, we found that the rs58542926 polymorphism of the TM6SF2 gene is associated with advanced liver fibrosis independent of rs738409 polymorphism of the PNPLA3 gene." (PMID 29258449, 2017). "In addition, this is the first study to investigates the relationship between the rs738409 (PNPLA3), rs58542926 (TM6SF2), rs1260326 and rs780094 (GCKR), rs641738 (MBOAT7), rs72613567 (HSD17B13), and rs2642438 (MTARC1) polymorphisms in the Brazilian population with MASLD and hepatic fibrosis." (PMID 40650184, 2025). "In the present study we showed that PNPLA3 and TM6SF2 gene polymorphisms significantly increased the risk of advanced fibrosis in patients with NASH, while more importantly, IR increased the risk of advanced liver fibrosis in non-diabetic patients." (PMID 35625751, 2022).
non-alcoholic fatty liver disease (27 papers, 2014 to 2026). "For instance, specific genetic variants interact with fish intake in influencing metabolic disease risk-such as the association between fish consumption and TM6SF2 gene variants in modulating non-alcoholic fatty liver disease risk." (PMID 40831670, 2025). "The transmembrane 6 superfamily member 2 located in the endoplasmic reticulum regulates lipid metabolism and is associated with the advancement of non-alcoholic fatty liver disease (NAFLD)." (PMID 38720280, 2024). "We have also identified tm6sf2, which is associated with both the risk and the severity of nonalcoholic fatty liver disease as well as with the regulation of inflammatory responses in atherosclerotic lesions." (PMID 37240180, 2023). "Current studies have shown that transmembrane 6 superfamily member 2 (TM6SF2) rs5854292 gene polymorphism is associated with nonalcoholic fatty liver disease." (PMID 31752753, 2019). "For example, the common PNPLA3 p.I148M, MBOAT7 p.G17E, and TM6SF2 p.E167K variants have been shown to increase the risk of liver steatosis, fibrosis, and cirrhosis in patients with nonalcoholic fatty liver disease (NAFLD), alcoholic liver disease (ALD), and with viral liver diseases." (PMID 34949757, 2021). "The adiponutrin (PNPLA3) p.I148M and transmembrane 6 superfamily member 2 (TM6SF2) p.E167K variants represent major genetic risk factors for progressive liver injury in nonalcoholic fatty liver disease (NAFLD), alcoholic liver disease (ALD) and chronic viral hepatitis." (PMID 30161167, 2018). "Previously, there was a study showing that adiposity significantly increases the effect of the three variants (PNPLA3-I148M, TM6SF2-E167K, and GCKR-P446L) associated with nonalcoholic fatty liver disease (NAFLD)." (PMID 38674389, 2024). "Several SNPS, such as rs11591147 in PCSK9, rs1260326 in GCKR, rs10455872 in LPA, rs964184 in ZPR1, rs58542926 in TM6SF2, and rs182611493 in MAU2 have been clinically associated with multiple metabolic disorders, including coronary heart disease, hyperlipidemia, non-alcoholic fatty liver disease." (PMID 41608459, 2026). "Non-alcoholic fatty liver disease (NAFLD) is thought to emerge from a state of insulin resistance (IR) as the product of an interaction between the obesogenic environment and genetically predisposing alleles (e.g., I148M in PNPLA3, E167K in TM6SF2, MBOAT7 rs641738 variant)." (PMID 31426291, 2019).
hepatocellular carcinoma (25 papers, 2017 to 2026). A malignant tumor that arises from hepatocytes. "We found that TM6SF2 rs58542926 T/C gene polymorphism had a significant association with hepatocellular carcinoma (T vs C, OR = 1.621; 95%CI 1.379–1.905; P = 0.000)." (PMID 31752753, 2019). "The occurrence of single nucleotide variants rs738409 in the PNPLA gene and rs58542926 in transmembrane 6 superfamily member 2 gene (TM6SF2) associate with the risk of hepatocellular carcinoma, whereas variant rs4607179 of hydroxysteroid 17-beta dehydrogenase gene (HSD17B13) reduces the risk." (PMID 34298760, 2021). "The result suggested that TM6SF2 gene mutation of E167K may promote DNA replication and accelerate cell cycle of human hepatocellular carcinoma cell line HEPA 1–6 and thereby promote the development of liver cancer cells." (PMID 28407767, 2017). "In oeder to investigate the effects of the polymorphism of TM6SF2 gene E167K in the pathogenesis of HCC, we explored its influence on the cell cycle in hepatocellular carcinoma cell HEPA1-6." (PMID 28407767, 2017). "In order to investigate the effects of the polymorphism of TM6SF2 gene E167K in then pathogenesis of HCC, we explored its influence on the cell cycle in hepatocellular carcinoma cell HEPA 1–6." (PMID 28407767, 2017). "Using the HuH7 hepatoma cell line, established from hepatoma tissue, two different manuscripts studied the effect of stable transmembrane 6 superfamily member 2 (TM6SF2) silencing." (PMID 39125855, 2024). "The polymorphism in the patatin-like phospholipase domain-containing 3 (PNPLA3) and the transmembrane 6 superfamily member 2 (TM6SF2) genes are associated with NAFLD, NASH, fibrosis, and an increased risk of hepatocellular carcinoma." (PMID 33505944, 2021). "Extension of PNPLA3 and TM6SF2 association has also been observed to hepatocellular carcinoma (HCC) attributable to both viral and non-viral origin, and less commonly to alcoholic liver disease." (PMID 36028802, 2022). "TM6SF2 silencing also inhibits APOB secretion in two human hepatoma cell lines." (PMID 32776921, 2020). "We observed in hepatoma cells that the silencing of the MBOAT7 and TM6SF2 genes led to an enhanced release of ccf-mtDNA, whose levels were conversely reduced in overexpressed cells." (PMID 40563253, 2025). "TM6SF2 is shown to facilitate the secretion of TG-rich very low-density lipoproteins (VLDLs), and to a lesser extent, that of apolipoprotein B (APOB) in human hepatoma cell lines." (PMID 32776921, 2020).
diabetes (21 papers, 2016 to 2025). "We previously investigated this cohort for variants in the PNPLA3 and TM6SF2 genes to identify people at a higher risk of liver steatosis (PNPLA3) and fibrosis (TM6SF2), a condition frequently associated with obesity, diabetes, and metabolic syndrome." (PMID 38649714, 2024). "It has been suggested that inhibition of TM6SF2 protects against cardiovascular disease, likely at the expense of increasing the risk for MASLD and diabetes." (PMID 38919271, 2024). "Insulin resistance, diabetes mellitus, and genetic variations in transmembrane 6 superfamily member 2 (TM6SF2) and patatin-like phospholipase domain containing 3 (PNPLA3) play important roles in NAFLD progression." (PMID 36188561, 2022). "The TM6SF2 variant rs58542926 known as p.E167K was associated with steatosis and fibrosis in NASH patients, independently of diabetes mellitus (DM), obesity or PNPLA3 variant." (PMID 34830997, 2021). "Subgroup analyses stratified by baseline fibrosis stage, diabetes status, and genetic polymorphisms (particularly PNPLA3, TM6SF2, and HSD17B13 variants) could identify patients most likely to benefit from SGLT2 inhibitor therapy." (PMID 40872510, 2025). "Concerning the potential role of LPIN1 rs13412852, KLF6 rs3750861, SOD2 rs4880, TM6SF2 rs58542926, and ZNF624 rs12603226 SNPs in glycemic control of the patients with diabetes, data are also limited." (PMID 34746177, 2021). "Another study of NAFLD patients who did not have diabetes and were not obese showed that PNPLA3 rs738409 I148M increased the risk for CKD, but TM6SF2 rs58542926 E167K reduced the risk for CKD." (PMID 37400794, 2023). "The TM6SF2 gene variant is associated with increased risks of NAFLD, NASH, and advanced fibrosis independent of age, body mass index (BMI), presence of diabetes, and PNPLA3 genotype status." (PMID 31447675, 2019). "Addition of genetic markers for the prediction of advanced fibrosis (baseline model: age, sex, BMI, diabetes: AUC 0.777) resulted in a higher AUC if PNPLA3(AUC 0.789), and TM6SF2(AUC 0.786) but not if HSD17B13(0.777) were added." (PMID 34076851, 2021).
Insulin resistance (18 papers, 2016 to 2026). Increased resistance towards insulin, that is, diminished effectiveness of insulin in reducing blood glucose levels. "Insulin resistance (IR), type 2 diabetes (T2D), and the polymorphisms patatin-like phospholipase domain-containing 3 (PNPLA3) rs738409 and transmembrane 6 superfamily member 2 (TM6SF2) rs58542926 are independent risk factors of NASH." (PMID 35625751, 2022). "Studies indicate ethnic disparities in NAFLD pathogenesis – for instance, African Americans exhibit distinct hepatic insulin resistance patterns compared to East Asians at comparable BMI levels, likely influenced by genetic variants such as PNPLA3 and TM6SF2 with population-specific effects." (PMID 40228278, 2025). "In addition, six loci were linked to insulin resistance, type 2 diabetes, or reduction in HbA1c levels in type 2 diabetes (APOB, HPR, TM6SF2, KSR2, JMJD1C, and SLCO1B1)." (PMID 38532495, 2024). "Hence, genetic factors may also provide a pathophysiological link between insulin resistance and MAFLD progression such as the E167K variant of TM6SF2." (PMID 36079118, 2022). "Emerging evidence supports genetic determinants of FLD (eg PNPLA3, TM6SF2, MBOAT7, GCKR, HSD17B13) as determinants of insulin resistance and T2D." (PMID 33102799, 2020). "Thus, the association with inflammation and fibrosis is likely independent of lipid accumulation and insulin resistance, and also of any other lipid-related variants such as PNPLA3 and TM6SF2." (PMID 27630043, 2016). "These genes include Patatin-like phospholipase domain containing 3 (PNPLA3), glucokinase regulatory protein (GCKR), and transmembrane 6 superfamily member 2 (TM6SF2), and are independent of insulin resistance." (PMID 37299398, 2023).
metabolic syndrome (14 papers, 2014 to 2025). A cluster of metabolic risk factors for CARDIOVASCULAR DISEASES and TYPE 2 DIABETES MELLITUS. "Variants increasing liver PDFF, such as those in PNPLA3 and TM6SF2, impair hepatic lipid export, promoting fat accumulation without systemic dyslipidemia." (PMID 40922984, 2025). "Additionally, visceral obesity, T2DM, dyslipidemia, and arterial hypertension are well-established risk factors promoting MASLD onset and progression, with genetic predispositions, such as PNPLA3 and TM6SF2 polymorphisms, further increasing susceptibility." (PMID 40219006, 2025). "Variants such as PNPLA3 and TM6SF2 have been associated with hepatic fat accumulation independent of metabolic syndrome, while lifestyle and environmental exposures—including diet composition, physical inactivity, and gut microbiome dysbiosis—may further influence disease expression." (PMID 41437157, 2025). "Emerging genetic evidence supports this notion in MASLD, showing that variants like PNPLA3 and TM6SF2, while strongly associated with hepatic fat and fibrosis, do not independently increase CVD risk in the absence of metabolic syndrome." (PMID 41567808, 2025).
fibrosis (12 papers, 2014 to 2026). the formation of excess fibrous connective tissue in an organ or tissue in a reparative or reactive process. "The gene TM6SF2 E167K variant (genotype CT) was also associated advanced fibrosis (p=0.00)." (PMID 29258449, 2017). "Genetic predisposition (especially variants in PNPLA3 and TM6SF2), metabolic dysfunction, and alcohol consumption are established risk factors for steatotic liver disease (SLD) and progression of fibrosis." (PMID 41492318, 2026). "Fifty-two per cent (50/97) of metabolites associated with NASH-fibrosis variants were also associated with liver fat variants, again the majority (86%, 43/50) were PC species due to similarity between GCKR and TM6SF2 metabolite associations." (PMID 32720691, 2020).
Obesity (12 papers, 2016 to 2026). Accumulation of substantial excess body fat. "Specifically, the most well-described variants are patatin-like phospholipase domain-containing protein 3 (PNPLA3) I148M, transmembrane 6 superfamily member 2 (TM6SF2) E167K and obesity-linked suppression of membrane-bound O-acyltransferase 7 (MBOAT7)." (PMID 34977507, 2022). "Secondly, this meta-analysis only involved single factor studies,the interactions of TM6SF2 gene polymorphisms and environmental factors, obesity, alcohol intake, intake of the fungal metabolite aflatoxin, and hepatitis B and C infections were not taken into consideration." (PMID 31752753, 2019). "The effects of TM6SF2, PNPLA3 and glucokinase gene regulator on NAFLD are additive in some individuals and can be augmented by obesity." (PMID 32776921, 2020).